RIMS2 (regulating synaptic membrane exocytosis 2)
Description:
Rab effector involved in exocytosis. May act as scaffold protein. Plays a role in dendrite formation by melanocytes.
Synonyms: KIAA0751; RAB3IP3; RIM2; OBOE; CRSDS
Tractability: Antibody: UniProt places it where antibodies can reach, with medium confidence; its Gene Ontology location is reachable by antibodies, with medium confidence; the Human Protein Atlas places it where antibodies can reach. PROTAC: its protein half-life has been measured.
Gene: Protein-coding gene on chromosome 8 (103,500,610 to 104,254,430, forward strand). Ensembl gene ENSG00000176406.
Subcellular location: Cell membrane; Synapse; Presynaptic cell membrane
Subcellular location (Human Protein Atlas): Cytosol; Plasma membrane
Gene Ontology:
Molecular function: protein binding; structural constituent of presynaptic active zone; transmembrane transporter binding; small GTPase binding
Biological process: positive regulation of dendrite extension; adenylate cyclase-modulating G protein-coupled receptor signaling pathway; calcium ion-regulated exocytosis of neurotransmitter; calcium-ion regulated exocytosis; insulin secretion; positive regulation of excitatory postsynaptic potential; positive regulation of inhibitory postsynaptic potential; regulation of exocytosis; regulation of membrane potential; regulation of synaptic vesicle exocytosis; spontaneous neurotransmitter secretion; synaptic vesicle priming; exocytosis; intracellular protein transport; maintenance of presynaptic active zone structure
Cellular component: extracellular exosome; presynaptic active zone; presynaptic active zone cytoplasmic component; presynaptic membrane; membrane; plasma membrane; synapse
Genetic constraint (gnomAD): Loss-of-function variants: 24 observed, 85.46 expected, observed/expected ratio (o/e) 0.28, 90% interval 0.2 to 0.4. The upper end of that interval is the gene's LOEUF score, 0.4, which puts it in group 1 of 6, group 1 being the genes least tolerant of losing a copy. Missense variants: 889 observed, 972.81 expected, observed/expected ratio (o/e) 0.91, 90% interval 0.86 to 0.97. Synonymous variants: 339 observed, 344.79 expected, observed/expected ratio (o/e) 0.98, 90% interval 0.9 to 1.08.
Homologues: Orthologues: macaque RIMS2 (95% identical), rat Rims2 (92% identical), mouse Rims2 (92% identical), pig RIMS2 (91% identical), dog RIMS2 (90% identical), rabbit RIMS2 (87% identical), tropical clawed frog RIMS2 (85% identical), guinea pig RIMS2 (81% identical), chimpanzee RIMS2 (75% identical), zebrafish RIMS2 (49% identical), Drosophila melanogaster Rim (34% identical), Caenorhabditis elegans unc-10 (28% identical), and 1 more. Paralogues in human: RIMS1 (59% identical), RIMS3 (13% identical), RIMS4 (11% identical), NANOGNB (3% identical).
Diseases named in the same sentence as RIMS2 in open-access papers:
RIMS2 is named in the same sentence as 26 diseases in open-access papers, as found by Europe PMC text mining. Sharing a sentence is not in itself a finding about the gene and the disease. The quoted sentences say what the papers report.
melanoma (3 papers, 2020 to 2023). A malignant, usually aggressive tumor composed of atypical, neoplastic melanocytes. "RIMS2 has been reported to be mutated in melanoma, and no other studies on the prediction of outcomes in patients with cancer have been reported." (PMID 34092242, 2021).
schizophrenia (3 papers, 2008 to 2023). A major psychotic disorder characterized by abnormalities in the perception or expression of reality. "Previous studies showed that RIMS2 was mainly involved in some nervous system diseases, such as schizophrenia, heroin addiction, and Autism Spectrum Disorder." (PMID 37020199, 2023). "RIMS2 codes for a protein that forms part of the cytomatrix of the active zone of synapses and was observed to be upregulated in the amygdala in schizophrenia." (PMID 18445270, 2008). "Furthermore, another study found upregulation of the RIMS2 gene in schizophrenia, implicating altered cytomatrix active region gene expression of synapses in the amygdala for dysfunction in the pathophysiology of schizophrenia." (PMID 35893077, 2022). "The expression of two previously reported putative genes for schizophrenia, RGS4 and RIMS2 was also measured." (PMID 18445270, 2008).
breast carcinoma (2 papers, 2021 to 2023). "Other regions included RIMS2, known to be associated with particularly aggressive breast cancers, and APIP, which binds HER3 receptor, leading to the heterodimerisation between HER2 and HER3 and resulting in sustained activation of downstream signalling." (PMID 36661191, 2023). "Immunoprecipitation experiments revealed that RIMS2 may promote anchorage-independent growth and colony formation of liver metastatic breast cancer cells by binding with claudin-2 gene via a PDZ-binding motif." (PMID 34211824, 2021).
myopia (2 papers, 2016 to 2025). "Among the mRNAs targeted by differentially expressed miRNAs, there were several (Prkar1a, Rims2, Map2, Gabarapl1, Htr7, Add3, Erc1, Nlgn1) which were involved in synapse formation and function suggesting that synaptic function was one of the biological processes affected in form-deprivation myopia." (PMID 27622715, 2016). "Subsequently, RIMS2 [odds ratio (OR) = 0.01, P = 0.0097] and LCA5 (OR = 9.27, P = 0.0089) were found to harbor an excess number of nonsynonymous variants in patients with slow progression of high myopia." (PMID 40091069, 2025).
Asperger syndrome (1 paper, 2023). "The involvement of RIMS2 in autism spectrum disease (ASD) is supported by a genome-wide association study in affected individuals with Asperger syndrome, revealing a significant association with the RIMS2-associated SNP rs2080610." (PMID 37179554, 2023).
autism (1 paper, 2018). Persistent deficits in social interaction and communication and interaction as well as a markedly restricted repertoire of activity and interest as well as repetitive patterns of behavior. "No study so far has reported the association of RIMS2 with genetic disorders, but its homologues RIMS3 and RIMS4 were implicated autism risk factors." (PMID 30619482, 2018).
cognitive disease (1 paper, 2022). "In a genome-wide survival study, RIMS2 was identified as a novel synaptic locus and polygenic score for cognitive disease progression in Parkinson’s disease (PD)." (PMID 35893077, 2022).
gastric cancer (1 paper, 2023). A primary or metastatic malignant neoplasm involving the stomach. "However, RIMS1, another member of the RAS gene superfamily with similar structure and function to RIMS2, has shown a promising prognostic value in several kinds of cancer, like gastric cancer." (PMID 37020199, 2023).
glioma (1 paper, 2023). A benign or malignant brain and spinal cord tumor that arises from glial cells (astrocytes, oligodendrocytes, ependymal cells). "It should also be noted that the function of KCNC1, KCNT1, RIMS2, NECAP2, GNG5, SCAMP2, GNAI3 genes is also correlated with membrane function in low-grade gliomas." (PMID 37239411, 2023).
oligodendroglioma (1 paper, 2023). A well-differentiated (WHO grade II), diffusely infiltrating neuroglial tumor, typically located in the cerebral hemispheres. "RIMS2 has also been reported to be associated with neuron-related functions and is specifically expressed in oligodendroglioma with 1p loss." (PMID 37239411, 2023).
Optic disc pallor (1 paper, 2021). A pale yellow discoloration of the optic disc (the area of the optic nerve head in the retina). "All seven reported cases of iCSNB associated with RIMS2, a regulator of synaptic membrane exocytosis localized to rod photoreceptors and the outer plexiform layer, from 3 unrelated, ethnically diverse families demonstrated clinically appreciable optic disc pallor." (PMID 33668843, 2021).
cancer (6 papers, 2010 to 2024). A tumor composed of atypical neoplastic, often pleomorphic cells that invade other tissues. "Several studies have suggested that abnormal expression of RIMS2 may involve in the development of cancer." (PMID 37020199, 2023). "Only limited evidence indicated that RIMS2 may also contribute to the development of cancer." (PMID 37020199, 2023). "The function of RIMS2 in ALL was also not explored previously and could only be indirectly reflected by the studies on other cancers." (PMID 34211824, 2021).
tumor (2 papers, 2022 to 2023). "This study found that RIMS2 methylation level was significantly higher in tumor compared to normal tissue, which results in low RIMS2 expression in CRC." (PMID 37020199, 2023).
psychiatric disorder (1 paper, 2024). A disorder characterized by behavioral and/or psychological abnormalities, often accompanied by physical symptoms. "We identified 7 genes (Cap2, Shc3, Lrrc7, Rims2, Cntnap2, Tcf20, and Trank1) associated with neurodevelopmental and psychiatric disorders that feature social impairments." (PMID 38263132, 2024).
RIMS2 also shares sentences with these, for which no sentence is quoted: nervous system diseases (2 papers); autism spectrum disorder (1); COVID-19 (1); genetic disorders (1); heroin addiction (1); lipodystrophy (1); lung adenocarcinoma (1); lung carcinoma (1); papillary thyroid carcinoma (1); Parkinson disease (1); periodontitis (1); skin cancer (1).